FLI1 (Fli-1 proto-oncogene, ETS transcription factor)
Diseases named in the same sentence as FLI1 in open-access papers (continued):
Sharing a sentence is not in itself a finding about the gene and the disease.
preeclampsia (6 papers, 2019 to 2024). Preeclampsia is a hypertensive disorder of pregnancy that is characterized by new-onset hypertension with proteinuria presenting after 20 weeks of gestation, and depending on mild or severe forms may initially present with severe headache, visual disturbances, and hyperreflexia. "While Fli-1 dependent mechanism remains well-established, the significance of another putative mechanism underlying vascular fibrosis in preeclampsia is more conflicting." (PMID 37628922, 2023). "Abnormal Fli1 activity is implicated in the development of hypertensive disorders such as uremic cardiomyopathy and preeclampsia." (PMID 36768203, 2023). "Another example of pathology at least partially associated with aberrantly low Fli1 expression and the development of vascular fibrosis is preeclampsia (PE), a hypertensive complication of pregnancy adversely affecting both mothers and newborns and in some cases leading to maternal stroke and death." (PMID 36768203, 2023). "As the vasoconstrictive effect via the Blaustein effect is temporary, the Fli-1-dependent fibrosis may be a mechanism implicated in increased long-term cardiovascular risk that persists after delivery in women who have undergone preeclampsia." (PMID 37628922, 2023). "Interestingly, the patients with preeclampsia, chronic renal failure, and type 2 diabetes shared the same phenotype features, namely the development of cardiovascular fibrosis due to Fli1 deficiency." (PMID 36768203, 2023). "Preeclampsia is another example of the condition associated with the activation of CTS and Fli1-dependent pro-fibrotic signaling." (PMID 39295945, 2024). "Preeclampsia is associated with a high plasma MBG level, a four-fold decrease in Fli1 level, and a three-fold increase in collagen-1 level in the umbilical arteries versus those from normal subjects." (PMID 39295945, 2024). "The effects of preeclampsia on Fli1 and collagen-1 were blocked by the in vitro treatment of umbilical arteries with 10 mol/L canrenone." (PMID 39295945, 2024). "The authors suggested that both Fli-1 and TGF-β are implicated in MBG-dependent fibrosis in preeclampsia." (PMID 37628922, 2023). "Incubation of healthy human umbilical arteries with nanomolar concentrations of MBG resulted in inhibition of Fli1 expression, increased synthesis of collagen-1, and impaired vasorelaxation, mimicking the effects of preeclampsia." (PMID 37628922, 2023). "The role of Fli-1-dependent fibrosis induced by MBG in preeclampsia is supported by extensive literature." (PMID 37628922, 2023). "We observed extremely high levels of MBG and low levels of Fli1 along with an extremely high level of collagen-1 in patients and experimental animals with preeclampsia, chronic renal failure and malignant hypertension." (PMID 33669287, 2021). "In patients with preeclampsia, MBG was elevated, vascular Fli1 was depressed, their umbilical arteries were stiff and fibrotic, and they failed to relax following enothelin-1-induced constriction." (PMID 39201581, 2024). "The goal of the present experiment was to comprehend the ability of the MBG/Fli1-dependent mechanism to induce vascular fibrosis in CKD, and therefore to extend our previous hypothesis for preeclampsia to the pathogenesis of chronic renal failure." (PMID 39201581, 2024). "Because two signaling pathways are known to modulate the profibrotic effects of MBG, a question arises whether the profibrotic effect of MBG may be initiated via SMAD-dependent TGFβ1 signaling, which was not the case for preeclampsia and CKD, where a key mechanism is Fli1 dependent." (PMID 39201581, 2024).
soft tissue sarcoma (6 papers, 2018 to 2025). A malignant neoplasm arising from muscle tissue, adipose tissue, blood vessels, fibrous tissue, or other supportive tissues excluding the bones. "Indeed, transcriptional deregulation is thought to drive malignant transformation in soft-tissue sarcomas harboring oncogenic fusions of FET genes with site-specific transcription factors, such as CHOP, FLI1, and CREB." (PMID 34375640, 2021).
autoimmune disease (5 papers, 2023 to 2025). A disorder resulting from loss of function or tissue destruction of an organ or multiple organs, arising from humoral or cellular immune responses of the individual to their own tissue constituents. "This review aims to summarize the emerging roles of Fli-1 in inflammation and autoimmune diseases, with a focus on elucidating the underlying molecular mechanisms and exploring the potential therapeutic implications." (PMID 40305194, 2025). "Recent studies have underscored the significance of Fli-1 in modulating inflammation and autoimmune diseases via the regulation of inflammatory responses." (PMID 40305194, 2025). "As research progresses, further exploration of Fli-1′s regulatory mechanisms and therapeutic applications could unlock new avenues for addressing inflammatory and autoimmune disorders." (PMID 40305194, 2025). "Moreover, over the past decades Fli1 has attracted great attention for its role in the etiology of several autoimmune diseases." (PMID 36768203, 2023).
clear cell sarcoma (5 papers, 2014 to 2024). A rare malignant neoplasm with melanocytic differentiation characterized by the presence of polygonal or spindle shaped clear cells. "Although characteristic to ES, the EWS/FLI-1 fusion may also occur with a lower frequency in other types of tumors (clear cell sarcoma, PNET, Askin tumor of the chest wall)." (PMID 25870707, 2014). "In keeping with this, TFs such as FLI1 and ATF1 acquire pioneering properties and bind otherwise-inaccessible genomic regions when fused to EWS in Ewing and clear cell sarcoma, respectively." (PMID 38275898, 2024).
fibrosis (5 papers, 2014 to 2024). the formation of excess fibrous connective tissue in an organ or tissue in a reparative or reactive process. "Later studies have strongly implicated the transcription factor Fli1 in the progressive cardiac fibrosis seen with experimental uremia." (PMID 36768203, 2023). "Furthermore, Fli1 increased expression has been linked to decreased cardiac fibrosis in a physiological model system of cardiac damage and may imply a regulatory role not previously recognized." (PMID 24971943, 2014). "In bleomycin-treated mice, bosentan prevented dermal fibrosis and increased Fli1 expression in lesional dermal fibroblasts." (PMID 24708674, 2014).
gastric cancer (5 papers, 2017 to 2025). A primary or metastatic malignant neoplasm involving the stomach. "The highest FLI1-expressing gastric cancer cell line, FU97, is an unusual variant of gastric cancer, showing alpha-fetoprotein production." (PMID 31231464, 2019). "Normal epithelial cells, intestinal metaplasia (IM), and low-grade dysplasia (LGD) showed higher FLI-1 nuclear staining compared to gastric cancer epithelial cells." (PMID 37047006, 2023). "Further, we characterized the expression of FLI1 in gastric cancer cell lines and determined the functional role of FLI1 in AGS gastric adenocarcinoma cells in culture by overexpression via lentiviral transduction." (PMID 31231464, 2019). "We asked if human gastric cancer cell lines also show similar reduced levels of FLI1 expression as compared to adenocarcinoma cells in vivo." (PMID 31231464, 2019). "In a comprehensive TMA study evaluating many different types of tumors by IHC, only 3% of stomach cancers (2/67) showed FLI1 positive staining, supporting our findings that FLI1 is commonly lost in gastric adenocarcinomas." (PMID 31231464, 2019). "Additionally, FLI-1 suppresses invasion and proliferation in gastric cancer, suggesting that FLI-1 is a tumor suppressor gene and a prognostic biomarker of survival." (PMID 37047006, 2023). "Moreover, FLI1 expression was lowest in microsatellite-unstable (MSI) tumors compared with other gastric cancer molecular subtypes." (PMID 31231464, 2019). "Therefore, our findings suggest a functional role of FLI1 in suppressing invasion of gastric cancer cells." (PMID 31231464, 2019). "One possible explanation for this observation is that FLI1 may play alternative roles and differentially affect survival in various gastric cancer sub-types characterized by different molecular pathways, histological differentiation and/or tumor microenvironment." (PMID 31231464, 2019). "First, we interrogated a transcriptional database derived from RNA-Seq data from human gastric cancer cell lines, and found that most of these cell lines do not express FLI1." (PMID 31231464, 2019). "Among the 19 uniquely identified genes, 7 (GSPT1, TFF3, KLF4, ITK, GNB2L1, FLI1, and GNG5) were not included in the KEGG gastric cancer pathway, indicating that they have not been previously recognized as canonical GAC-related genes." (PMID 41284725, 2025).
pancreatic cancer (5 papers, 2009 to 2021). "GDSC analysis showed that mTOR inhibitors are very sensitive to pancreatic cancer cells with mutations in EWSR1.FLI1 and RNF43." (PMID 34461940, 2021). "In 42 primary pancreatic tumors the RNA-expression of the FLI1 targets DKK1, INPP5D, IGFBP3 and additionally two members of the Wnt/β-catenin pathway, namely BCL9 and BCL9L, was investigated using quantitative real time PCR." (PMID 27539223, 2016). "In a supplemental movie we show how a pancreatic tumour cell is slowly traversing through the caudal vein of a 3 dpt Tg(fli1:eGFP) zebrafish." (PMID 19400945, 2009). "In pancreatic adenocarcinomas the Akt pathway is activated by IGF and the ratio of IGF and its inhibitor IGFBP3, another target of EWS/FLI1, may play a role in the development of pancreatic cancer." (PMID 27539223, 2016).
vascular tumors (5 papers, 2013 to 2024). "Immunohistochemically, vascular endothelial markers such as Von-Willebrand factor, CD34, CD31 and Fli-1 are commonly positive in most of tumors at varying intensities in each case, which help identify and diagnose the tumor as a type of vascular neoplasms." (PMID 24063649, 2013). "In addition, expression of FLI-1 has been demonstrated in vascular neoplasms such as angiosarcoma and hemangioendothelioma." (PMID 38280044, 2024). "The FLI-1 protein has been shown to show certain effectiveness in the identification of vascular tumors, including EHE, and it was also recognized as an endothelial cell marker with a combined sensitivity and specificity superior to those of widely used endothelial markers alone." (PMID 35347504, 2022). "ERG and FLI1 are relatively sensitive and specific markers of vascular tumors, regardless of the type and level of malignancy 9,10." (PMID 39845895, 2024).
B-cell lymphomas (4 papers, 2019 to 2025). "Both A661 and A665 significantly reduced Fli-1 protein expression in the B-cell lymphoma cells line Daudi." (PMID 30741932, 2019). "In contrast to HL, ETS1 and FLI1 are aberrantly upregulated in subsets of DLBCL, pointing to differences in the pathogenesis of these B-cell lymphomas." (PMID 37428779, 2023). "B-cell lymphoma cell line U-2932 expressed elevated NKX2-4 and reduced FLI1, suggesting that the repressive impact of NKX2-4 may play a role in malignant lymphoid cells as well." (PMID 34768865, 2021).
chronic renal failure (4 papers, 2021 to 2024). "Marinobufagenin (MBG) is implicated in chronic kidney disease, where it removes Fli1-induced inhibition of the collagen-1." (PMID 39201581, 2024). "For example, Fli1-dependent vascular fibrosis is a hallmark of renal failure in partially nephrectomized rats and in patients with end-stage renal disease." (PMID 35328757, 2022).
epithelioid angiosarcoma (4 papers, 2013 to 2025). "Immunostaining is positive for CD31, CD34, FLI-1, AE1/AE3, and CK7, diagnostic of primary epithelioid angiosarcoma." (PMID 32983683, 2020). "Coexpression of mesenchymal (vimentin) and endothelial (particularly CD31 and Fli-1) markers along with epithelioid histopathological features confirms diagnosis of epithelioid angiosarcoma." (PMID 23844302, 2013).
Immunodeficiency (4 papers, 2021 to 2022). Failure of the immune system to protect the body adequately from infection, due to the absence or insufficiency of some component process or substance. "The deletion of the FLI-1, ETS1, JAM3 and THYN1 genes was considered to be directly associated with the immunodeficiency exhibited by the patient." (PMID 34440371, 2021). "FLI1 gene is also reported to be closely related to immune dysfunction and platelet disorders." (PMID 35529472, 2022). "The expression of the THYN1 gene in these immune cells leads us to propose its implication in the immunodeficiency of JBS patients, along with FLI-1, ETS1, NFRKB and JAM3." (PMID 34440371, 2021). "Genetically, FLI1 and ETS1 are seen as causative for the immunodeficiency, but these genes were deleted nor duplicated in 4 of our 14 patients." (PMID 35763218, 2022). "ETS1 and FLI1 involvement did not correlate to patients with immunodeficiency of B nor T lymphocyte dysfunction in our cohort." (PMID 35763218, 2022).
metastatic tumors (4 papers, 1994 to 2024). "We have analysed tumour-derived material from 30 ET patients with well-documented clinical course (18 with localised and 12 with metastatic disease at diagnosis) for the presence of EWS/FLI-1 or EWS/ERG RNA." (PMID 7524604, 1994).
oral cancer (4 papers, 2017 to 2024). "In addition, we used transparent in vivo imaging analysis of tumor metastasis by microinjecting Dil-labeled, stably transfected oral cancer cell lines into the perivitelline space of Tg (fli-1: EGFP) zebrafish for 3 days to observe cell invasion." (PMID 35963855, 2022). "In addition, several downstream targets of these specific microRNAs were upregulated by all oral cancer cell lines, such as MBTD1 and FSCN1, or downregulated in all cell lines, such as CLCN3, FLI-1, MRTFB, DAB, SRGAP1, and ABHD17C." (PMID 38396844, 2024). "As shown, NNMT, FLI1, SLPI, LAMP3, SERPINA1, GAS6, and CD274 have been often used as biomarkers for OSCC or head and neck cancer, while other genes listed have seldom been investigated in oral cancer and may be considered as novel biomarkers for OSCC prevalence and treatment." (PMID 28286742, 2017).
Paris-Trousseau syndrome (4 papers, 2018 to 2024). "The clonal anomaly in the BM of one further patient was a complex unbalanced translocation with partial monosomy of the long arm of chromosome 11 implying the loss of the FLI1 gene, consequently hypo-expressed and leading to diagnosis of Paris-Trousseau type thrombocytopenia." (PMID 29344089, 2018).
pulmonary arterial hypertension (4 papers, 2018 to 2024). Pulmonary arterial hypertension (PAH) is a group of diseases characterized by mean pulmonary artery pressure >20 mmHg and elevated pulmonary arterial resistance leading to right heart failure. "On the other hand, FLI1 deficiency is also implicated in the development of pulmonary arterial hypertension (PAH) by modulating the expression of angiogenesis-related genes." (PMID 34774095, 2021).
Sepsis (4 papers, 2023 to 2025). Sepsis is defined as life-threatening organ dysfunction caused by a dysregulated host response to infection. "Through the modulation of NFκB signaling and regulated by miR-145a, Fli-1 has been confirmed to be involved in the regulation of sepsis-associated microvascular dysfunction and organ injury." (PMID 40305194, 2025). "Our findings indicate that an increased expression of Fli-1 in lung pericytes may contribute to pericyte pyroptosis and the knockout of Fli-1 in pericytes attenuates lung pericyte loss, vascular leak, and mortality in a murine model of sepsis." (PMID 37566011, 2023). "Second, knockout of Fli-1 in pericytes protects against the early neuroinflammatory response in sepsis." (PMID 39862276, 2025). "In conclusion, our findings underscore the crucial role of brain pericytes in the early inflammatory response during sepsis and reveal a novel function of Fli-1 in regulating brain pericyte-mediated inflammation." (PMID 39862276, 2025). "Collectively, these results highlight a novel role for brain pericytes in mediating early neuroinflammation during sepsis and underscore the critical role of Fli-1 in brain pericyte activation." (PMID 39862276, 2025). "We observed that Fli-1 knockout in pericytes mitigated sepsis-induced lung injury, and Fli-1 knockdown in cultured lung pericytes reduced inflammatory responses, indicating that Fli-1 in lung pericytes contributes to lung inflammation during sepsis." (PMID 39862276, 2025). "Consistent with this, we observed that knockout of Fli-1 in pericytes reduced the early inflammatory response in the brain during sepsis." (PMID 39862276, 2025). "Our previous studies highlighted that activated lung pericytes contribute to sepsis-induced inflammation via Friend leukemia virus integration 1 (Fli-1)." (PMID 39862276, 2025). "Specifically, Fli-1 knockout in these cells attenuated the inflammatory response, reduced vascular leakage, and decreased mortality in a murine sepsis model." (PMID 39862276, 2025). "WT and pericyte-specific Fli-1 knockout mice were subjected to endotoxemia through LPS injection or sepsis via cecal ligation and puncture (CLP)." (PMID 39862276, 2025). "Previous research has implicated friend leukemia virus integration 1 (FLI1), an erythroblast transformation-specific (ETS) transcription factor, in inflammatory responses in sepsis and Alzheimer’s disease." (PMID 39140108, 2024). "We hypothesize that pericytes mediate the early neuroinflammatory response in sepsis through Fli-1 and that Fli-1-mediated pericyte activation contributes to this response by producing MCP-1." (PMID 39862276, 2025). "Fli-1 in pericytes may serve as a crucial mediator of neuroinflammation during sepsis by directly regulating pivotal cytokines such as MCP-1 and IL-6." (PMID 39862276, 2025). "Therefore, targeting Fli-1 to prevent pericytes activation could potentially reduce initial inflammation in organs affected by inflammatory diseases like sepsis and improve clinical outcomes." (PMID 39862276, 2025). "Thus, targeting brain pericyte Fli-1 may offer a new strategy for addressing initial process of neuroinflammation in sepsis and neuroinflammation-related conditions." (PMID 39862276, 2025). "Therefore, Fli-1 may contribute to the pathogenesis of sepsis and represents a novel therapeutic target due to its direct impact on transcription of inflammatory mediators." (PMID 40305194, 2025). "However, the role of pericyte Fli-1 in neuroinflammation during sepsis remains largely unknown." (PMID 39862276, 2025). "In this study, we further confirmed that elevated levels of Fli-1 in brain pericytes increase MCP-1 expression, thereby contributing to the early inflammatory response in the brain during sepsis." (PMID 39862276, 2025).
Sepsis (continued). "Thus, activated brain pericytes may play a role in the initial inflammatory response during sepsis through the release of cytokines and chemokines mediated by LPS-induced TLR4/Myd88 signaling, with Fli-1 acting as a crucial regulator in this process." (PMID 39862276, 2025).
acute promyelocytic leukemia (3 papers, 2018 to 2025). An aggressive form of acute myeloid leukemia (AML), characterized by arrest of leukocyte differentiation at the promyelocyte stage, due to a specific chromosomal translocation t(15;17) in myeloid cells. "Based on our analysis of the Beat AML dataset, we observe a positive correlation between adverse overall survival and high FLI1 and ELF1 transcript levels in all non-acute promyelocytic leukemia patients, especially in CN-AML where MEIS1 levels are high." (PMID 35624144, 2022).